CKB (creatine kinase B)
Diseases named in the same sentence as CKB in open-access papers (continued):
Sharing a sentence is not in itself a finding about the gene and the disease.
CKB also shares sentences with these, for which no sentence is quoted: Alzheimer disease (5 papers); COVID-19 (3); cardiac arrest (2); diabetes (2); Hypertension (2); hypoxic-ischemic encephalopathy (2); ischemia (2); multiple sclerosis (2); myocardial infarction (2); psychiatric disorder (2); sarcoma (2); anorexia nervosa (1); aortic aneurysm (1); Aortic dissection (1); asphyxia (1); autoimmune disease (1); behavioral disorders (1); bone tumor (1); breast tumour (1); central nervous system disease (1); Cirrhosis (1); Cognitive impairment (1); dementia (1); encephalitis (1); endocervical adenocarcinoma (1); endometriosis (1); gastric adenocarcinoma (1); hepatic disorders (1); hepatoblastoma (1); herpes simplex infection (1).
A further 18 diseases each share a sentence with CKB in 1 paper.